TNF (tumor necrosis factor)
Diseases named in the same sentence as TNF in open-access papers (continued):
Sharing a sentence is not in itself a finding about the gene and the disease.
rosacea (continued). "In in vitro experiments, the study found that TLR2 and S100A9 protein levels increased in HaCaT cells under conditions simulating rosacea, and the cytokines IL6, OSM, and TNF‐α were significantly elevated, implying their potential promoting roles in the progression of rosacea." (PMID 39823143, 2025). "Overexpression of TLR2 in rosacea patients may stimulate elevated production of pro-inflammatory cytokines, such as IL-8, IL-1β, and TNF-α, exacerbating the inflammatory response." (PMID 41009424, 2025). "Notably, cytokines such as TNF-α, IL-6, and IL-8 stimulate nociceptors, leading to the burning and stinging sensations commonly experienced by rosacea patients." (PMID 41383625, 2025). "Furthermore, GE1111 reduced the LL-37-induced gene expression of MCP-1, IL-31, and TNF-α in MCs, which upregulated in rosacea." (PMID 41296102, 2025). "Furthermore, gene expression analysis revealed elevated levels of inflammatory cytokines IL-13, IL-33, MCP-1, IL-1β, and TNF-α in LL-37-treated mice, consistent with rosacea’s symptoms and serum MCP-1 level." (PMID 41296102, 2025). "Moreover, GE1111 treatment significantly decreased the gene expression of inflammatory cytokines, including IL-31, MCP-1, and TNF-α in MCs, which are critical in rosacea’s inflammatory response." (PMID 41296102, 2025). "In addition, RT‐qPCR analysis of inflammatory factors in skin tissue revealed that the expression levels of IL‐6, OSM, and TNF‐α were significantly higher in rosacea patients than in the healthy control group." (PMID 39823143, 2025). "Our functional enrichment analysis showed several interleukin and Tumor Necrosis Factor (TNF) played roles in rosacea and PLC, immune and inflammation pathways may also contribute to the onset and progression of PLC." (PMID 40286597, 2025). "The presence of SIBO might provoke rosacea by amplifying levels of TNF or other cytokines, inhibiting IL-17, and initiating the T helper 1-mediated immune response." (PMID 38585146, 2024). "The gut bacteria may also mimic immunogens, potentially leading to upregulation of TNF-α, suppression of IL-17, stimulation of T-helper 1 immunity, and subsequent development or exacerbation of rosacea." (PMID 39583431, 2024). "So, we speculated that MLT repressed the IL-17, NF-κB, and TNF signaling pathways by targeting these pharmacological targets, subsequently leading to inflammation and angiogenesis in AD and rosacea." (PMID 34899707, 2021). "The GO/KEGG enrichment results indicated that anti-AD and anti-rosacea effects exerted by MLT were directed via regulating vascular-associated signaling pathways and inflammation-related signaling pathways, including IL-17, NF-κB, and TNF." (PMID 34899707, 2021). "Moreover, studies demonstrated the potential relationship between MLT target genes (MMP9, CCND1, EGFR, ICAM1, PTGS2, and SERPINE1) and rosacea-related key genes (IL-6, IL-1β, IFNγ, IL-17, and TNF-α)." (PMID 34899707, 2021). "The suggested pathomechanism involved in the association between rosacea and SIBO could be explained by increases in shared circulating cytokines, especially tumor necrosis factor-alpha." (PMID 33182618, 2020). "Activation of immune-mediated inflammatory pathways appears central to the pathogenesis of rosacea and involves the coordinated activity of several cell types, such as mast cells and macrophages, and the release of proinflammatory mediators, such as IL-6, IL-1β, and TNF-α." (PMID 39247187, 2024). "The Gene Ontology/Kyoto Encyclopedia of Genes and Genomes results indicated that LXWHT may exert therapeutic effects on rosacea by intervening in immune pathways including tumor necrosis factor pathway, interleukin-17 pathways, and Toll-like receptor signaling pathways." (PMID 38941423, 2024).
rosacea (continued). "In addition, topical ivermectin 1% treatment for 12 weeks significantly decreased Demodex density and downregulated IL-8, LL-37, TLR-4, human β-defensin 3 (HBD3), and tumor necrosis factor α (TNF-α) gene expression, implicating anti-inflammatory effects along improving clinical course of rosacea." (PMID 38260914, 2023). "Moreover, TNF-α and IL-17A were also reported as the key cytokines in AD and rosacea." (PMID 34899707, 2021). "The probiotic intervention exerted a symptom-relieving effect on rosacea, as evidenced by significantly lowered PGA scores, reduced TNF-α levels, and improved SC hydration." (PMID 39475254, 2024). "In LL37-induced rosacea-like mice, ART and its derivatives significantly inhibited the expression of pro-inflammatory factors (IL-1β, IL-6, and TNFα) and TLR2." (PMID 35950034, 2022). "The results of RT-qPCR showed that carvedilol alleviated the elevated inflammatory cytokines (TNF-α, IL-6, and IL-8) and macrophage chemotactic factors (ITGAM, ITGB2) of rosacea-like skin, indicating that inflammation and macrophages are inhibited." (PMID 34322115, 2021). "Skin samples of patients with rosacea were subjected to histopathological (hematoxylin and eosin) and immunohistochemical (CD68, Toll-like receptor 2 (TLR2), kallikrein 5, cathelicidin, TNF-α, and IL-1β) evaluation." (PMID 34322115, 2021). "Tranexamic acid, an antifibrinolytic agent recently used to treat melasma in Asian patients, improves rosacea by reducing IL-6, TNFα, and MMP expression, and also lowers the angiogenesis of rosacea by reducing VEGF expression and the number of CD31+ cells." (PMID 34769465, 2021). "In patients with rosacea, the overexpression of TLR2 may stimulate elevated pro-inflammatory cytokine production (IL-8, IL-1β, and TNF-α, etc.), exacerbating the inflammatory response." (PMID 41009424, 2025). "Elevated levels of disease characteristic factors, such as KLK5, CAMP, TLR2, and proinflammatory cytokines (such as TNF‐α, IL1β, and IL6), and MMPs have been observed in the skin lesions of human rosacea patients as well as in a mouse model of rosacea induced by LL37." (PMID 39692542, 2024). "Taken together, these findings indicate the following: first, rosacea is characterized by predominant Th1/Th17 cytokine signatures, and second, rosacea is driven by early overexpression of type I IFN during acute flare-ups, which then is subsequently relayed by TNF and a chronic inflammation." (PMID 36633910, 2023). "Inflammation in rosacea and IBD is mediated by activation of macrophages and toll-like receptor 2, dysregulation of mast cells, fibroblasts, and generation of reactive oxygen species, matrix metalloproteinases, tumor necrosis factor, and interleukin-114,21." (PMID 37689807, 2023). "Moreover, MLT repressed the expression of proinflammatory cytokines, such as IL-6, TNF-α, TLR2, TGF-β1, MMP9, and VEGF in rosacea-like dermatitis." (PMID 34899707, 2021). "Rosacea skin lesions exhibited more pronounced inflammatory cell infiltration than peripheral areas, with profound macrophage infiltration and inflammatory cytokines (TLR2, kallikrein 5, cathelicidin, TNF-α, and IL-1β)." (PMID 34322115, 2021). "In rosacea, proteomic and transcriptomic investigations have revealed enrichment of neurodegeneration-related proteins such as SNCA, GSK3B, and HSPA8, as well as regulatory hubs including PPARG, STAT4, and RORA, which converge on NF-κB, IL-17, and TNF signaling pathways." (PMID 41465136, 2025). "TNF-α and IL-1β are known to induce the expression of a subset of proinflammatory chemokines (CXCL1, CXCL8, CCL20, and CCL27) in keratinocytes, implying a potential pathway for TH1 and TH17 cell recruitment as well as neutrophil recruitment in rosacea lesional skin." (PMID 35832851, 2022). "Furthermore, IL-1β and TNF-α have an additional role as angiogenic factors VEGF; thus, these cytokines might explain the vascular hyper-reactivity seen in rosacea." (PMID 27649161, 2016).
rosacea (continued). "Among innate cytokines, we observed a significant increase in TNF, IL1B, IL8, IL12B, IL23A, and IL10 — but not IL36B — in rosacea skin lesions as compared with skin from healthy donors." (PMID 36633910, 2023).
Zinc deficiency (48 papers, 2009 to 2025). A deficiency of the essential metal Zinc; an essential cofactor for many enzymes. "This oral supplementation also reduced the elevated serum levels of the pro-inflammatory cytokines IL-6 and TNF-α induced by zinc deficiency." (PMID 40871688, 2025). "Zinc deficiency increases the proinflammatory cytokines’ production, such as IL-1β, IL-6, and TNF-α, as well as induces oxidative stress due to its scavenging properties against reactive oxygen species (ROS)." (PMID 41427149, 2025). "Zinc deficiency has been shown to decrease the production of TNF-α, IFN-γ and IL-2 by peripheral blood mononuclear cells." (PMID 40072975, 2025). "For example, zinc deficiency has been shown to increase the production of ROS and inflammatory cytokines (TNF-α, IL-1β, and IL-8)." (PMID 39683406, 2024). "Chronic zinc deficiency in a chick model triggered a decrease in gene expression of pro-inflammatory cytokines (IL-1β, IL-6, TNF)." (PMID 35344152, 2023). "Zinc deficiency has been shown to increase the release of proinflammatory cytokines, such as interleukins IL-1β, IL-6, and tumor necrosis factor (TNF)-α." (PMID 37435275, 2023). "Consistently, another study demonstrated that zinc deficiency reduced the production of interferon-gamma, interleukin-2 (IL-2), and tumor necrosis factor-alpha (TNF-α)." (PMID 37049478, 2023). "that TNF-α with zinc deficiency increases Caspase-8 activity and that zinc administration prevents this zinc-deficiency-induced apoptosis supports our results." (PMID 38022538, 2023). "In SAM children, zinc deficiency has been linked to elevated levels of pro-inflammatory cytokines such as interleukin-6 (IL-6) and tumor necrosis factor-alpha (TNF-α)." (PMID 38068727, 2023). "Serum changes associated with zinc deficiency also include an increase in Tumor Necrosis Factor-alpha (TNF-a) and pro-inflammatory cytokines and a decrease in anti-inflammatory cytokines such as interleukin-2 (IL-2) and interleukin-4 (IL-4)." (PMID 35353297, 2022). "According to previous studies, zinc acts as a crucial immune mediator against infection and inflammation, zinc deficiency enhances the generation of IL-1β and TNF-α in myeloid cells via epigenetic effects." (PMID 35602082, 2022). "Similar to our results, studies in both murine and human primary monocytes had shown zinc deficiency to impair TLR4-mediated signaling that resulted in reduced production of cytokines such as TNF-α, IL-6, IL-10, and Il-1β." (PMID 36558553, 2022). "Maternal zinc deficiency has been associated with elevated maternal serum TNF-α and IL-8 and small-for-gestational-age births." (PMID 34836049, 2021). "Sickle cell disease is characterized by elevated serum TNF-α and Th2 dominance, possibly exacerbated by zinc deficiency." (PMID 34239993, 2021). "Previously published studies underlined that zinc deficiency appears to promote the production of proinflammatory cytokines such as IL-1β, tumor necrosis factor alpha (TNFα), and IL-6 by myeloid cells and activated monocytes/macrophages." (PMID 34934131, 2021). "Zinc deficiency resulted in activating monocytes-macrophages, which resulted in increased generation of inflammatory cytokines such as TNF-α, IL-1β, and IL-6 and increased oxidative stress." (PMID 32411807, 2020). "Zinc deficiency also decreases the production of Th1 cytokines (TNF-α, IL-2, and IFN-γ), whereas the Th2 cytokine response (IL-10, IL-6, and IL-4) is less affected." (PMID 32944394, 2020). "TNF-α plays an important role in the mechanism of diarrhea in zinc deficiency, while serum TNF-α level can be used as a sign of inflammation that triggers the production of cytokines." (PMID 32148672, 2019). "For example, zinc deficiency increases the levels of TNF-α, IL-1β, and IL-8 in a monocyte-macrophage cell line." (PMID 30622979, 2018).
Zinc deficiency (continued). "The potential of zinc deficiency to skew the inflammatory reaction is supported by experiments in pro-myeolid (HL-60) cells, which increased production of IL-1B and TNFα after zinc depletion." (PMID 29731970, 2018). "In effect, zinc deficiency is responsible for an alteration in the macrophage function and a reduction of production of tumor necrosis factor (TNF-α) and interferon-γ (INF-γ)." (PMID 28399817, 2017). "Zinc deficiency increases the production of proinflammatory cytokines, such as interleukins IL-1β, IL-6, and tumor necrosis factor (TNF)-α." (PMID 28629136, 2017). "Pre-incubation of differentiated intestinal Caco-2 cells with these juices conferred protection from the inflammatory stress induced by tumor necrosis factor α (TNFα) under marginal zinc deficiency." (PMID 27529258, 2016). "Zinc deficiency has been suggested to exacerbate the detrimental effects of specific fatty acids, such as linoleic acid, and inflammatory cytokines, such as TNF-α, on vascular endothelial functions." (PMID 22852057, 2012). "Zinc deficiency influences the generation of cytokines, including IL-1β, IL-2, IL-6, and TNF-α, and in response to zinc supplementation plasma cytokines exhibit a dose-dependent response." (PMID 22852057, 2012). "The generation of a variety of cytokines, including IL-1β, IL-2, IL-6, and TNF-α, is reportedly influenced by mild to moderate zinc deficiency in humans." (PMID 22852057, 2012). "The data obtained indicate that zinc deficiency is associated with an increase in TNF response by 37%; 95% CI: 14% to 118% and IFN-γ response by 74%; 95% CI: 24% to 297%." (PMID 20546583, 2010). "Overall, zinc deficiency was associated with increased supernatant concentrations of TNF and IFN-γ (by 37% and 74%, respectively), and seemed associated with increased concentrations of IL-5 and IL-13." (PMID 20546583, 2010). "Zinc deficiency leads to the activation of monocytes/macrophages, which generate free radicals, causing oxidative stress and triggering the production of cytokines such as tumor necrosis factor (TNF-α), interleukin IL-1β, and IL-6." (PMID 38138191, 2023). "Zinc deficiency predisposes people to infectious and inflammatory diseases and increases the production of pro-inflammatory cytokines: interleukin-6, interleukin-8, and tumor necrosis factor." (PMID 35330104, 2022). "Zinc deficiency increases the production of proinflammatory cytokines, such as interleukin IL-1β, IL-6, and tumor necrosis factor (TNF) α, which may exacerbate damage to normal tissue." (PMID 36471454, 2022). "In monocytes, zinc deficiency reduces the production of IL-6 and TNF-α." (PMID 33375344, 2020). "Zinc deficiency in humans activates monocytes-macrophages, which generate free radicals leading to oxidative stress and upregulate generation of inflammatory cytokines such as TNF-α, IL-1β, and IL-6." (PMID 32411807, 2020). "The presence of an immune response in zinc deficiency is proven through an increase of TNF-α and IL-6 level before intervention and conversely, the reduction in the immune response is characterized by a decrease in TNF-α and IL-6 level after zinc administration." (PMID 32148672, 2019). "Therefore, both CRP and serum albumin have been reported to be associated with elevated CRP, IL-6, TNF-α, IL-1β, and zinc deficiency." (PMID 30941358, 2019). "In addition, a recent study found that zinc deficiency reduces the production of IL-6 and TNF-α in human monocytes." (PMID 30622979, 2018). "In humans, Zinc deficiency has been reported to cause an imbalance between Th1 and Th2 cells: the Th1 function is decreased, while Th2 function is not affected, with increase in the production of IFNγ, IL-2, and tumour necrosis factor α (TNFα)." (PMID 27143960, 2016).
Zinc deficiency (continued). "After PMA or LPS stimulation, human derived-promyelocytic leukemia (HL-60) and human vascular endothelial cells cultured in 1 μM zinc (zinc-deficiency) demonstrated significantly higher generation of TNF-α and IL-1β cytokines than cells cultured in 15 μM zinc (physiologic conditions)." (PMID 22852057, 2012). "However, the overall effects of zinc deficiency on the production of IL-6 and TNF-α remain unclear, as the results are inconsistent depending on the compound and the dose of cell-stimulation (e.g., lipopolysaccharide (LPS) vs. phytohaemagglutinin (PHA))." (PMID 33375344, 2020). "Zinc deficiency has a dose-dependent response to plasma cytokines, as zinc prevalence affects the production of cytokines, such as interleukins (IL-1β, IL-2, and IL-6) and tumor necrosis factor alpha (TNF-α) by MT homeostasis, which is, in turn, affected by proinflammatory cytokines." (PMID 33255662, 2020). "Zinc deficiency is associated with increased production of proinflammatory cytokines, such as IL-6, TGF-β, and TNF-α." (PMID 41614883, 2025). "As a result of zinc deficiency, the production of some proinflammatory cytokines, such as IL-6, TGF-β, and TNF-α can increase." (PMID 41614883, 2025). "A large category of cytokines, including IL-4, IL-6, interferon-g (IFN-g), TNF-α from innate immunity, and IL-2, TNF, and IFN-γ from adaptive immunity were found to be inhibited in production in patients with zinc deficiency." (PMID 35211497, 2022). "For instance, zinc deficiency reduced production of Th1 cytokines, in particular IFN-γ, IL-2, and tumor necrosis factor (TNF)-α, whereas levels of Th2 cytokines IL-4, IL-6, and IL-10 were not affected." (PMID 29196724, 2017). "Zinc deficiency decreases production of the Th1 cell cytokines, IFN-γ, IL-2, and tumor necrosis factor (TNF)-α, which play major roles in tumor suppression." (PMID 21087493, 2010). "During zinc deficiency, the production of TH1 cytokines, in particular IFN-γ, IL-2, and tumor necrosis factor (TNF)-α is reduced, whereas the levels of the TH2 cytokines IL-4, IL-6, and IL-10 were not affected in cell culture models and in vivo." (PMID 19523191, 2009). "When zinc deficiency was experimentally induced in young subjects, they showed significant effects on the production of IFN-γ, IL-2, and TNF-α with an imbalance in the TH1/TH2 system, but plasma zinc was not significantly affected." (PMID 19523191, 2009). "Previous studies explained the contribution of zinc deficiency to the increased risk of VOCs in SCD patients because zinc deficiency increases gene expression and production of interleukin 1β (IL-1β) and tumor necrosis factor α (TNF-α)." (PMID 40461893, 2025). "This suggests that after SCI, zinc deficiency promotes neuronal apoptosis not through mitochondrial intrinsic pathway but through extrinsic pathway mediated by TNF-α." (PMID 38022538, 2023). "Zinc deficiency in mast cells prevents translocation of PKC and downstream events such as the phosphorylation and nuclear translocation of NFκB as well as the downstream production of the cytokines IL-6 and TNFα." (PMID 21087493, 2010).